FGF21 (fibroblast growth factor 21)
Diseases named in the same sentence as FGF21 in open-access papers (continued):
Sharing a sentence is not in itself a finding about the gene and the disease.
myocardial infarction (57 papers, 2013 to 2025). Gross necrosis of the myocardium, as a result of interruption of the blood supply to the area, as in coronary thrombosis. "The investigations have shown an association between elevated FGF21 levels and hypertension, cardiac disease, myocardial infarction, atrial fibrillation, and cardiac atrial fibrosis." (PMID 38139126, 2023). "On the other hand, based on another clinicaltrial, acute myocardial infarction was also associated with a decrease incirculating FGF21 levels." (PMID 39077619, 2022). "After adjusting for demographic and clinical covariates such as age, gender, body mass index, diastolic blood pressure, HbA1c and previous myocardial infarction, the biomarker FGF21 remained in a significant association with the odds of HF (p = 0.001)." (PMID 34573919, 2021). "The cardioprotective effect of FGF21 was shown in the mouse model of myocardial infarction caused by the permanent ligation of the left anterior descending coronary artery (LAD)." (PMID 30671457, 2018). "In the mouse model of myocardial ischemia/reperfusion injury, FGF21 was upregulated, and this reduced cell death and myocardial infarction in association with an improvement of myocardial function." (PMID 26091256, 2015). "We further evaluated the short-term (24 hrs) effect of FGF21 on the degree of myocardial infarction in reference to the area at risk." (PMID 24067542, 2013). "Given that myocardial infarction is a common cause of HFrEF, FGF21 may reduce the risk of subsequent HF via this protective mechanism." (PMID 36028609, 2023). "In addition, liver-specific deficiency of FGF21 in mice with myocardial infarction resulted in further worsening of cardiac dysfunction." (PMID 36618930, 2022). "However, cardiac FGF21 expression has also been shown to increase in failing human hearts and in patients undergoing acute myocardial infarction, and as such has been described as an independent risk factor for increased carotid artery intima-media thickness." (PMID 35046901, 2021). "Administration of recombinant FGF21 (50 ng/gm for each dose, 2 doses per day with a 12 hr interval for a total period of 3 days) to FGF21−/− mice caused a significant drop in the fraction of myocardial infarcts compared to PBS administration." (PMID 24067542, 2013). "Here, we test the therapeutic efficacy of FGF21 in mice with ischemia–reperfusion (I/R) injury, a model of acute myocardial infarction." (PMID 40072149, 2025). "Recent studies using microarray gene expression and proteomic profiling have demonstrated elevated FGF21 protein levels in both hepatic and adipose tissues following myocardial infarction in mice." (PMID 41234361, 2025). "In a mouse model of myocardial ischemia, the liver responds by upregulating the expression and release of cardioprotective proteins such as FGF21, contributing to cardiac protection during myocardial infarction." (PMID 41234361, 2025). "Preclinical research indicates that FGF21 plays a bidirectional regulatory role in pathological states such as myocardial infarction, pressure-overload-induced cardiac hypertrophy, and heart failure." (PMID 41234361, 2025). "Inhibition of mineralocorticoid receptor (MR) expression or treatment of hepatocytes with the MR antagonist spironolactone has been shown to enhance FGF21-mediated cardiac repair and reverse pathological remodeling following myocardial infarction." (PMID 41234361, 2025). "A 6-week aerobic exercise training program increases the expression of FGF21 in the hearts of myocardial infarction (MI) mice." (PMID 40861271, 2025). "The release of FGF21 from the liver and adipose tissue was reported to reduce cell death and to attenuate myocardial infarction in mice." (PMID 37880253, 2023). "FGF21 also has a protective role in myocardial infarction survivors by inhibiting cardiomyocyte apoptosis and mitigating myocardial remodelling and infarct size via an adiponectin-dependent mechanism." (PMID 36028609, 2023).
myocardial infarction (continued). "Recently, Fgf21 biology has rapidly expanded to include protective roles against pathologic cardiac hypertrophy, oxidative stress, myocardial infarction, and skeletal muscle atrophy in rodents." (PMID 37511159, 2023). "Previous studies demonstrated that IL-22 protects against myocardial infarction by stimulating hepatic FGF21 expression." (PMID 37432218, 2023). "First, elevated levels of FGF21 in ischemic heart injury, including myocardial infarction, inhibit the phosphorylation of PPARγ, which is the active form of PPARγ, thus suppressing adipose browning in WAT." (PMID 37667400, 2023). "The cardioprotective properties of FGF21 in myocardial infarction, ischemia-reperfusion injury, or intense beta-adrenergic stimulation have been found in animal models and myocardial cell cultures." (PMID 38139126, 2023). "FGF21 can effectively ameliorate cardiac inflammation and fibrosis after myocardial infarction by regulating FGFR-EGR1, and more profoundly, to improve heart function." (PMID 35677107, 2022). "In myocardial infarction mice model, a new discovery shows that FGF21 ameliorates cardiac fibrosis via inhibiting TGF-β1-Smad2/3-MMP2/9 signaling pathway and concurrently exerts heart-protecting function." (PMID 35677107, 2022). "In the patients with AMI, the expressions of FGF21 were significantly increased in the first 24 h after myocardial infarction and maintained a high level for 1 week." (PMID 36440004, 2022). "Further following myocardial infarction, adiponectin-null mice receiving FGF21 treatment had a blunted FGF21 response, which resulted in decreased capillary density, increased myocyte apoptosis and increased proinflammatory cytokine expression." (PMID 32156043, 2020). "We have previously reported that FGF21 attenuates adverse cardiac remodeling in mice after myocardial infarction." (PMID 32584895, 2020). "Skeletal muscle-derived FGF-21 improved cardiac function reduced apoptosis and proinflammatory cytokines after myocardial infarction." (PMID 33317180, 2020). "In fact, FGF21 also exerts a cardioprotective effect post myocardial infarction through the activation of an adiponectin-dependent pathway." (PMID 31712677, 2019). "FGF21 also protects the heart from ischemic–reperfusion injury and myocardial infarction by activating Akt-glycogen synthase kinase (GSK)-3β-caspase-3 dependent pathway." (PMID 30185439, 2018). "In the study, the suppression of FGF21 expression by small interfering (si)RNA-mediated gene silencing resulted in a significant increase in the fraction of myocardial infarcts." (PMID 28582462, 2017). "Other studies have reported that FGF21 also exerts protection after myocardial infarction by inhibiting cardiomyocyte apoptosis, attenuating pathological myocardial remodeling, and reducing infarct size." (PMID 26379627, 2015). "Taken together, these very recent novel findings reveal new roles and mechanisms of action of FGF21 in the heart after myocardial infarction." (PMID 26379627, 2015). "FGF21−/− mice exhibited a significant increase in the fraction of myocardial infarcts compared to wild-type mice at 5, 10, and 30 days following myocardial ischemia/reperfusion injury." (PMID 24067542, 2013). "Moreover, skeletal muscle-derived FGF21 has been shown to modulate cardiac remodeling in mouse models of myocardial infarction." (PMID 41234361, 2025). "Additionally, exogenous FGF21 administration has been shown to reduce BCAA accumulation in mice following myocardial infarction." (PMID 41117265, 2025). "Therefore, our research highlights a viable strategy for the enhanced delivery of therapeutical FGF21 analogs to lesions beyond the liver following myocardial infarction." (PMID 40072149, 2025). "In addition, increased serum levels of FGF21 have been observed in patients with acute myocardial infarction (AMI), along with higher serum fatty acid binding protein-4 (FABP4) and saturated fatty acid levels." (PMID 37667400, 2023).
myocardial infarction (continued). "Furthermore, FGF21 attenuates acute myocardial infarction by upregulation of adiponectin in mice, and a high circulating FGF21 level is considered as a prognostic biomarker in patients with AMI." (PMID 35463746, 2022). "For example, upregulation of FGF21 may reduce myocardial infarction size after I/R injury through FGFR1–PI3K–AKT pathway." (PMID 36440004, 2022). "Further studies have found that the intervention of exogenous FGF21 significantly improved the survival of cardiomyocytes under ischemia and decreased the areas of myocardial infarction, whereas it inhibited the expression of FGFR1 increased the infarct area of ischemic myocardium." (PMID 34777697, 2021). "Another study in mice showed that the expression of FGF21 in the liver and the serum levels of FGF21 were increased in response to experimental myocardial ischemia, and the administration of FGF21 was shown to mitigate myocardial infarction." (PMID 28582462, 2017). "Although the exact reason for the increase is unclear, this finding may be secondary to pancreatitis-induced inflammation, as FGF21 has been shown to play a role in other inflammatory conditions and disease states such as myocardial infarction." (PMID 27832059, 2016). "The overexpression of FGF21 by adenoviral vectors in the skeletal muscle of mice (Ad-FGF21 mice) improves left ventricular systolic dysfunction and dilatation in a mouse model of myocardial infarction." (PMID 27803896, 2016). "However, the FGF21 level was lower than in those with myocardial infarction." (PMID 39194718, 2024). "FGF21 has also been shown to protect against myocardial infarction (MI) and post-MI ventricular arrhythmia by regulating inflammation, fibrosis, and the action potential duration of cardiac myocytes." (PMID 39335642, 2024). "Furthermore, serum FGF-21 concentration is elevated after myocardial infarction." (PMID 33317180, 2020). "However, the regulation of FGF21 expression during acute myocardial infarction (AMI) remains unclear." (PMID 31413360, 2019). "Based on this, another study in a mice model with myocardial infarction (MI) investigated that 6-week aerobic exercise (10 m/min, 55 min/day, 5 days/week) elevated the protein expression of FGF21 and FGFR1 in cardiomyocytes, as well as decreased oxidative stress and apoptosis." (PMID 40003929, 2025). "FGF21 through the mediation of the FGFR1/β-Klotho–PI3K–Akt1–BAD signaling network to reduce cell death, and myocardial infarction thereby ameliorating myocardial function." (PMID 38789571, 2024). "Simultaneously, increased Fgf21 has been found to inactivate the TGF-β1-Smad2/3-MMP2/9 signaling pathway and alleviate cardiac fibrosis to improve cardiac function in mice with myocardial infarction." (PMID 37511159, 2023). "Moreover, an experiment in an animal model of acute myocardial infarction has shown that miR-124-3p targets SIRT1 to influence cell apoptosis, inflammatory responses, and oxidative stress through regulation of the FGF21/CREB/PGC1α axis." (PMID 37441551, 2023). "Administration of FGF21 decreased the mRNA expression of interleukin-6 (IL-6) and tumor necrosis factor-α (TNF-α) and protected against pathological myocardial remodeling and improved cardiac function at 2 weeks in a myocardial infarction mouse model." (PMID 36440004, 2022). "Aerobic exercise (48% of VO2max for 6 weeks) also significantly reduces oxidative stress (H2O2) and apoptosis by activating the Fibroblast growth factor 21 (FGF-21)/FGFR1/PI3K/AKT pathway, which ultimately improves heart function in mice with myocardial infarction." (PMID 36036015, 2022). "Emerging evidence has shown a beneficial effect of FGF21 on cardiovascular diseases, but the role of FGF21 on ventricular arrhythmias following myocardial infarction (MI) in humans has never been addressed." (PMID 34630093, 2021).
myocardial infarction (continued). "This study further elucidates the protective mechanism of exercise on the ischemic heart and suggests that FGF21 and ALCAT1 may be important molecular targets for clinical treatment or prevention of myocardial infarction." (PMID 34777697, 2021). "Recently, it was demonstrated that the levels of FGF21 in circulation are promoted in CHD and that FGF21 could attenuate pathological heart remodeling in myocardial infarction." (PMID 30157856, 2018). "Moreover, serum FGF21 levels have been shown to predict major cardiac adverse events in humans, including non-fatal myocardial infarction, non-fatal stroke, hospitalization due to angina pectoris, and cardiac death." (PMID 35046901, 2021).
non-alcoholic steatohepatitis (55 papers, 2014 to 2025). "PsTag-FGF21, a long-acting FGF21 analogue, has shown positive therapeutic effects for metabolic dysfunction-associated steatohepatitis (MASH)." (PMID 38962005, 2024). "A recent study reported that plasma FGF21 is associated with severity of nonalcoholic steatohepatitis in obese patients with T2DM." (PMID 34660809, 2021). "FGF21 may be able to affect the proliferation of hepatocellular carcinoma cells, as lack of FGF21 has been reported to promote liver cancer associated with metabolic stress such as long-term obesogenic diet feeding or nonalcoholic steatohepatitis." (PMID 35321438, 2022). "In a clinical trial, weekly subcutaneous injection of efruxifermin (a long-acting Fc-FGF21 fusion protein) effectively reduced hepatic fat fraction in non-alcoholic steatohepatitis patients and was generally well tolerated." (PMID 38292187, 2024). "I-WD mice also developed nonalcoholic steatohepatitis, associated with an increase in type-III collagen gene expression and a decrease in FGF21 protein levels, in comparison with SD." (PMID 38474774, 2024). "There is also a positive correlation between plasma FGF21 and the severity of steatohepatitis, particularly fibrosis, in patients with non-alcoholic steatohepatitis." (PMID 38292187, 2024). "In phase 2b trials, treatment of nonalcoholic steatohepatitis (NASH) with pegozafermin (a glycopegylated fibroblast growth factor 21 analog) led to improvements in fibrosis." (PMID 39064306, 2024). "FGF-21 was report to enhance skeletal muscle glucose uptake and protect lipid disruption and nonalcoholic steatohepatitis, even in a clinical trial." (PMID 38643166, 2024). "In the latest studies, FGF21 has come to the fore as an emerging therapeutic target for nonalcoholic steatohepatitis and related metabolic diseases." (PMID 35677107, 2022). "The latest research evidence confirms that FGF21 can improve metabolic status with anti-fibrotic effects and has the potential treatment for non-alcoholic steatohepatitis (NASH)." (PMID 34675822, 2021). "A study using the same FGF21 analogue molecule as ours (LY2405319) showed improvements in nonalcoholic steatohepatitis in ob/ob mice by enhancing hepatic mitochondrial function." (PMID 32957703, 2020). "Fibroblast growth factor 21 (FGF21), a hormone-like protein, plays a crucial role in enhancing glucose and lipid metabolism, offering promising therapeutic avenues for conditions such as nonalcoholic steatohepatitis and severe hypertriglyceridemia." (PMID 40141314, 2025). "Moreover, a PEGylated human fibroblast growth factor 21 (FGF21) analogue pegbelfermin has also been shown to significantly reduce liver fat fraction in patients with nonalcoholic steatohepatitis." (PMID 37576954, 2023). "Supplementation of FGF21 or its analogists could be conductive to alleviating the development of nonalcoholic steatohepatitis (NASH)." (PMID 37091847, 2023). "Moreover, the inhibition of FGF21 expression also promoted the transformation of nonalcoholic steatohepatitis to hepatitis." (PMID 37576954, 2023). "In animal models with nonalcoholic steatohepatitis (NASH), the administration of FGF21 analogues was associated with reduced expression of several proinflammatory cytokines, including tumor necrosis factor a (TNF-a), interleukin-6 (IL-6), IL-1, and interferon-γ (IFN-γ)." (PMID 35200696, 2022). "Pegozafermin, a long-acting glycopegylated analog of human fibroblast growth factor 21, is in development for the treatment of severe hypertriglyceridemia (SHTG) and nonalcoholic steatohepatitis." (PMID 37355760, 2023). "In studies of patients with non-alcoholic steatohepatitis (NASH), pegylated versions of FGF21 produced significant decreases in hepatic fat, markers of hepatic fibrosis, and liver injury." (PMID 34917032, 2021).
non-alcoholic steatohepatitis (continued). "These FGF21 analogues have a longer half-life than the natural protein and have been tested in patients with hypertriglyceridemia but also in patients with NAFLD and non-alcoholic steatohepatitis (NASH)." (PMID 35107764, 2022). "FGF21 was also recently proven to be an independent predictor and marker of NAFLD in humans, and its pharmacological administration has been proposed as an effective treatment to Non-alcoholic steatohepatitis NASH." (PMID 32708435, 2020). "Preclinical studies investigating the long-acting FGF21 analogue, B1344, in non-human primates with non-alcoholic steatohepatitis (NASH) demonstrated reduction of steatosis, attenuation of inflammation and fibrosis, and reduced hepatocyte injury after 11 weeks of therapy." (PMID 37249754, 2023). "Therefore, a phase 2B clinical trial has been investigated to examine whether pegbelfermin (a novel long-acting FGF21) has therapeutic effects on nonalcoholic fatty liver disease (NAFLD) and nonalcoholic steatohepatitis (NASH)." (PMID 33799938, 2021). "Elevated FGF21 levels have been associated with multiple liver diseases, including alcoholic liver diseases (ALD), NAFLDs, non-alcoholic steatohepatitis (NASH), hepatocellular carcinoma (HCC), and hepatitis, although the role of FGF21 in the progression of these diseases has not been defined." (PMID 26594197, 2015).